CD4 (CD4 molecule)
Diseases named in the same sentence as CD4 in open-access papers (continued):
Sharing a sentence is not in itself a finding about the gene and the disease.
cancer (continued). "Engineered cancer-specific CD4+ T cells may contribute to protective immunity by a direct pathway involving cancer cell killing, and by an indirect pathway that boosts the function, persistence and memory formation of CD8+ T cells." (PMID 32708397, 2020). "In addition to the risk factors of the general population, advanced cancer stages, increased TNF-α, and decreased clusters of differentiation 4 (CD4) T cells and albumin globulin ratios were risk factors for the disease in cancer patients." (PMID 33232275, 2020). "Collectively, our results suggest that Ocs-P could improve DC maturation inhibited by cancer progression, and this DC maturation may contribute to the upregulation of multifunctional CD4+ and CD8+ T cells." (PMID 33105813, 2020). "Furthermore, FCGR1A was notably associated with infiltrating levels of CD4+ T cells, CD8+ T cells, B cells, macrophages, neutrophils, and dendritic cells in the four cancers (P < 0.05)." (PMID 33344503, 2020). "Indeed, in an HIV-1-infected individual who had uncontrolled metastatic squamous cell carcinoma, an HIV-1-infected CD4+ T cell clone expanded as the tumor progressed and contracted when cancer treatment was initiated." (PMID 31910871, 2020). "In addition to providing essential ‘help’ for functional CD8+ T-cell responses, CD4+ T cells can also display killing activity and, when adoptively transferred in murine models, provide effective cancer immunity." (PMID 32708397, 2020). "In this study, we demonstrated that decreased levels of NK cells, CD8+ T cells, naïve CD4+/CD4+ T cells, and elevated percentages of the following T cells were associated with cancer incidence: memory CD4+/CD4+, CD8+ HLA‐DR+/CD8+, CD8+ CD38+/CD8+, and CD4+/CD8+." (PMID 32459060, 2020). "In addition, many cancer-associated peptide epitopes recognized by CD8+ T cells have been identified, while the knowledge of ‘helper’ epitopes recognized by CD4+ T cells is relatively sparse." (PMID 32708397, 2020). "The frequency of CD4+ T cells and Treg remained stable for young and elderly cancer patients." (PMID 32082401, 2020). "It is well-recognized that CD4+ T cells may play an important role in immunosurveillance and immunotherapy against cancer." (PMID 33083004, 2020). "Since the predictions made in this report are for peptides with a large coverage of MHC-II alleles in the human population, experimental validation will prove of great relevance to better understand the role of TERT CD4 T cell immunity in immune surveillance and for immunotherapy of cancer." (PMID 32630460, 2020). "However, there is a substantial amount of data indicating a key role of CD4+ T cells in cancer immunity." (PMID 32708397, 2020). "CD4+ Tregs have been revealed as a key player in many inflammatory diseases, including cancer." (PMID 31970893, 2020). "Presence of such CD4+ epitope(s) in a cancer vaccine is highly undesirable." (PMID 32570805, 2020). "Altogether, monitoring of anti-TERT CD4 T cell responses in vitro could greatly help refine the stratification of cancer patients and predict clinical outcome in response to immune checkpoint blockade." (PMID 32630460, 2020). "Also, expression levels of ACE2 were significantly correlated with infiltration levels of B cells, CD8 + T cells, CD4 + T cells, macrophages, neutrophils, and dendritic cells in 13, 11, 5, 10, 16, and 15 cancer types." (PMID 33088807, 2020). "Indeed, CD4+ T helper cells are crucial to elicit a strong and durable immune response against cancer cells." (PMID 32806719, 2020). "However, the main role of CD4+ T cells in the immune response to cancer is to prime CD8+ T cells and maintain their proliferation." (PMID 33170901, 2020).
cancer (continued). "There were additional correlations between TGFβ2 and the levels of CD8+T cell infiltration in 19 cancer types, CD4+T cell infiltration in 21 cancer types, macrophage infiltration in 23 cancer types, neutrophil infiltration in 23 cancer types, and dendritic cell infiltration in 23 cancer types." (PMID 32530106, 2020). "In addition, the expression of calreticulin on the surface of cancer cells can be recognized and processed by macrophages which then activate CD4+ and CD8+ T-cells." (PMID 32656079, 2020). "The role of CD4 + TILs in immune activity has been reported in many cancer patients." (PMID 32222891, 2020). "An important role of CD4 T cells in cancer defense has been formerly outlined elsewhere." (PMID 32799890, 2020). "On the other hand, CD4 or CD8 single-positive T cells play major roles in cancer immunology." (PMID 32132638, 2020). "This applies not only to cancer but also other pathologies where inflammation might unleash the intrinsic capacity of ILCs to act as promoters of CD4+ T-cell responses." (PMID 32341343, 2020). "Moreover, percentages of CD4+ T cells were decreased with corresponding increase in the percentages of CD8+ T cells in cancer patients’ PBMCs." (PMID 33230147, 2020). "Conversely, the levels of CD4 T cells were significantly reduced in cancer tissue." (PMID 33426064, 2020). "TIMER showed PRDM1 positively correlated with the abundance of CD8+ T cell in the all cancer types with prognostic significance while it also positively correlated with the abundance B cell, CD4+ T cell, Neutrophil, Macrophage and Dendritic cell in all the other cancer types except UVM." (PMID 33384601, 2020). "Previous studies reported higher incidence of cancer in KTR with low T CD4 cells levels." (PMID 32903778, 2020). "Moreover, CD4+ chimeric antigen receptor T cells display cytolytic activity, implicating cytotoxic functions of CD4+ T cells in cancer immunotherapy." (PMID 32102981, 2020). "We built a network of interactions involving intracellular relationships and cytokine-mediated intercellular relations that combine published models of different cell types relevant to PDAC, namely, (epithelial) cancer cells, stellate cells, CD4+ T cells, CD8+ T cells, and macrophages." (PMID 32696951, 2020). "Moreover, DHX37 expression also significantly correlated with CD8 T cells, CD4 T cells, B cells, macrophages, neutrophils, and dendritic cells (DCs) in 16, 19, 12, 18, 16, and 14 types of cancer, respectively." (PMID 33490290, 2020). "The interconnectedness of these two important cytotoxic cells has not been clearly delineated previously even though correlations were seen in increased percentages of NK and CD8+ T cells in peripheral blood and in bone marrow (BM) of cancer patients in the presence of decrease in CD4+ T cells." (PMID 33230147, 2020). "Finally, there has been an assumption that the ‘killing function’ of CD8+ T cells is more important in protection against cancer than the ‘helper function’ of CD4+ T cells." (PMID 32708397, 2020). "Specifically, relative lymphocytopenia may reflect lower levels of CD4 + T cells, which impairs cancer immune surveillance and defense." (PMID 33060826, 2020). "Finally, flavonoids also have anti-proliferative effects on cancer cells through suppression of the PI3k/Akt/mTOR pathway and activation of T CD4+." (PMID 32138292, 2020). "Furthermore, the presence of CD4+ T cell help in clinical cancer studies correlated with the induction of cytotoxic CD8+ T cell responses." (PMID 32674488, 2020). "Therefore, cancer vaccines should contain both CD4+ and CD8+ T-cell epitopes to allow for antigen presentation in MHC class I and II." (PMID 33255564, 2020). "CD4+ TILs mediate an anti-cancer immune response by activating tumoricidal CD8+ T-cells." (PMID 33216833, 2020).
cancer (continued). "Moreover, the single application of αCTLA-4 checkpoint inhibitors increased the frequency of antigen-specific IFNγ producing ICOS+ CD4+ T cells correlating with a better therapeutic outcome in human cancer patients." (PMID 32674488, 2020). "Moreover, CD4+ T cells are essential for cancer immunity via mechanisms that have been recently reviewed." (PMID 33013886, 2020). "Other cells, including endothelial cells, CD4+ T cells, and CD8+ T cells accounted for a relatively large proportion, while B cells, carcinoma-associated fibroblasts (CAFs), macrophages, and natural killer (NK) cells accounted for a relatively small proportion." (PMID 32457797, 2020). "Moreover, KLRC1 expression has positive correlations with infiltrating levels of B cells in 23 cancer types, CD4+ T cells in 20 cancer types, macrophages in 17 cancer types, neutrophils in 31 cancer types, and dendritic cells in 32 cancer types." (PMID 32010126, 2019). "For the CD4+ T cell subtypes, we also compared the candidate marker genes identified from the DE analysis with the Tregs marker genes reported by four previously published scRNA-seq data from different cancer types." (PMID 31324168, 2019). "CD4+ T cells have several means by which to kill cancer cells." (PMID 31362778, 2019). "Indeed, 19305DP-TCR-transduced CD4+ T cells significantly induced expression of the apoptotic marker annexin V and PI on cell surface of cancer cells after 24-h co-culture." (PMID 30626427, 2019). "Interestingly, we observed a positive correlation between frequency of CD45RChigh on CD4+ and CD8+ T cells suggesting that, as a double-edged sword, patients prone to AR before transplantation also have a lower risk of experiencing cancer." (PMID 30925186, 2019). "These antitumor roles of CD4+ Th1 cells are mainly driven by the triad of cytokines, such as IFN-γ, TNF-α and IL-2.5,6 Furthermore, a clinical benefit associated with Th1-polarised signature in the TME has been reported in many human cancers." (PMID 31358938, 2019). "CD4+ T cells are essential for control of many infectious diseases and cancer." (PMID 31608052, 2019). "Furthermore, FUNDC1 expression was also significantly correlated with the infiltration levels of B cells, CD8+ T cells, CD4+ T cells, macrophages, neutrophils, and dendritic cells in 10, 20, 16, 16, 19, and 19 cancer types, respectively." (PMID 31998650, 2019). "In our first exploratory study, immune senescence was significantly higher in elderly cancer patients than in age-matched controls; in particular, cancer patients, compared to controls, exhibited similar percentages of senescent CD4 lymphocytes, but higher percentages of senescent CD8 cells." (PMID 31195370, 2019). "CTLA-4 expression on CD4 cells was increased with 190% in cancer patients before treatment compared to healthy controls, and RT induced a further strong and persistent increase in CTLA-4 expression (212% increase one month after RT compared to pre-treatment levels)." (PMID 31500214, 2019). "Importantly, higher CD4+/CD8+ T cells ratios have been correlated with increased survival rate in cancer patients." (PMID 31906092, 2019). "The splenic immunophenotye of mice with advanced cancer showed the emergence of the hyaluronic acid receptor CD44+ and in a smaller extent IL-17A+ MDSCs, the loss of B220+ and CD62L+ B-cells, the loss of CD62L+ CD4+ and CD8+T-cells." (PMID 31881770, 2019). "Also, the frequency of PD-1 intermediate CD4+ T cells was higher in the BAL from cancer affected lung than peripheral blood while frequency of PD-1 low cells was lower in clBAL." (PMID 31010080, 2019). "Experiments conducted on TSLP receptor-deficient mice indicated that TSLP might play an essential role in protection and metastasis of cancer cells through its receptor on CD4+T cells." (PMID 31023965, 2019).
cancer (continued). "Indeed, mechanistic studies investigating the role of M2 macrophages in chronic models of fibrosis and cancer have suggested that M2 macrophages slow the suppression of local CD4+ T cell responses and reduce ECM production by myofibroblasts." (PMID 31747961, 2019). "A decreased number of CD4+ and CD8+ T cells might be implicated in autoimmune and inflammatory disorders; many chronic diseases, including cancer, are linked to inflammation disorder." (PMID 31296257, 2019). "As cytotoxic CD8+ effector function is highly dependent on CD4+ T-cell cooperation, exploration of cellular and biochemical drivers TH-cell differentiation may hold promise for making resistant cancers more immunogenic." (PMID 30926808, 2019). "Indeed, the involvement of NK, CD8 and CD4 T cell influences the cancer immunity cycle in several aspects." (PMID 31291991, 2019). "Effector T cells, especially CD8+ and CD4+ T cells, get the most attention in cancer dormancy." (PMID 31297335, 2019). "Cancer cells that are recognized by the CD4+ and CD8+ T cells can be eliminated." (PMID 31602007, 2019). "This strategy has provided a broader idea of the frequency of neoantigen reactivities in cancer patients and is capable of detecting CD4+ T-cell responses targeting neoantigens, which may be important to develop effective treatments." (PMID 31293573, 2019). "CD4 T cells are one of the inhibiting cell types for cancer." (PMID 31138124, 2019). "Indeed, the appearance of a specific murine subtype of CD4 T cell was the main correlator with efficacious responses by administration of anti‐cancer cell immunoglobulins." (PMID 31273938, 2019). "BBR was shown to inhibit STAT3 activation in cancer cells and CD4+ T cells." (PMID 30894513, 2019). "We observed that there was a positive association trend between neoantigen loads and both T cell CD8+ and CD4+ memory-activated types in all cancer types except thyroid and kidney (Binomial test P = 0.11 and P = 0.02 for T cell CD8+ and CD4+ memory-activated types, respectively)." (PMID 31533728, 2019). "Therefore, any consideration of adoptive immune cell therapy or cancer vaccines should include promoting the development of antigen-specific memory CD4+ T cells." (PMID 31379821, 2019). "Furthermore, a crosstalk between CD4+, GATA3+ T cells and cancer-associated fibroblasts was identified that resulted in greater infiltration of Th2 T cells and decreased patient survival." (PMID 31068602, 2019). "Additionally, memory resting CD4+ T cells is differentially infiltrated in cancer tissues of patients with different PBMC subtypes in HER2+ patients (P = 0.034) and HER2-enriched patients (P = 0.037)." (PMID 31632916, 2019). "In a Th1 microenvironment, pro-inflammatory cytokines may participate in cancer eradication by attracting leucocytes from circulation and by augmenting CD4+ T-cell action." (PMID 31185596, 2019). "Furthermore, anti-cancer resting memory CD4+ T cells were significantly lower in Early and Mid BSD and pro-cancerous regulatory T cells were significantly higher in Mid and Late BSD compared to Survivors." (PMID 31729458, 2019). "The ability of in vitro generated TAM to inhibit CD8+ and CD4+ T cell proliferation suggests that targeting TAM in the setting of cancer could enhance NK and T cell function for improved cancer control." (PMID 31138333, 2019). "The poor prognosis could be explained by the observation that CD4 is expressed in most regulatory T cells that promote cancer progression." (PMID 31234828, 2019). "Furthermore, FOXP3, so called scurfin, is critically involved in differentiation and function of regulatory T cells or CD4+/CD25+ regulatory T (Treg) cells for cancer immunotherapy." (PMID 31815635, 2019). "Likewise, a prevalent activation of CD4+ Treg lymphocytes can decrease immunosurveillance and promote a protumoral switch of the immune system in cancer patients." (PMID 31114760, 2019).
cancer (continued). "Simultaneously, immune cells such as CD4 and macrophage could infiltrate the cancer cells, resulting in their death." (PMID 31817179, 2019). "19305DP recognized A*02+NY-ESO-1+ cancer cells in a CD4- and CD8-independent manner." (PMID 30626427, 2019). "Furthermore, Treg depletion and subsequent cancer antigen vaccination can initiate antitumor CD4+ T cell responses." (PMID 31906017, 2019). "A higher number of EpCAM+ CD4+ T cells are observable in the carcinoma tissue images." (PMID 31354723, 2019). "Carcinoma-associated pancreatic fibroblasts promoted the expression of CTLA-4 and PD-1 in proliferating T cells, which contribute to immune evasion by inducing the expression of immune checkpoint inhibitors on CD4+ and CD8+ T cells in PDAC." (PMID 31464648, 2019). "Our finding that HK2 function can be dispensed with for CD4 T cell function could come as welcome news to the cancer therapy field." (PMID 29352298, 2018). "Moreover, we identified an increased frequency of Ki-67+ divided CD4+ T cells in cancer septic hosts relative to previously healthy septic hosts." (PMID 29338031, 2018). "Thus, we conclude that the CD4+ T cell compartment in cancer septic hosts is one of increased activation and differentiation." (PMID 29338031, 2018). "The peptide containing the HLA-DP4-restricted epitope could also generate HLA-A2-restricted CD8+T cells, suggesting that the peptide could be used as a cancer vaccine to induce both CD4+ and CD8+ T cell responses." (PMID 29770138, 2018). "Moreover, increasing evidence of a link between CD8 and CD4 T-cell recognition of mutant neoepitopes and clinical responses to cancer immunotherapy strategies has been reported; for review, see Ref." (PMID 29403496, 2018). "Furthermore, beside IFN-γ, cancer-specific CD4 T cells can also secrete IL-4, establish long-term memory immune responses to tumors, and recruit eosinophils and macrophages." (PMID 29032503, 2018). "In addition, most cancer vaccine studies focus on the selection of CD8 T cell neo-epitopes while overlooking CD4 T cell neo-epitopes." (PMID 30400835, 2018). "Similar to cancer settings, chronic filarial infection with continuous release of parasite antigens is associated with a lack of CD4+ T cell proliferation and production of IFN-γ and IL-2." (PMID 29668679, 2018). "In contrast, the role of CD4 T cell immunity to cancer is much less understood." (PMID 29032503, 2018). "Our data suggest that monocytes that are exposed to MDA (and other cancer cell lines, S5 Fig) have significantly decreased their ability to promote allogeneic CD4+ and CD8+ and autologous CD4+ T cell proliferation as compared to unexposed monocytes, suggesting a suppressive phenotype." (PMID 29668679, 2018). "Finally, functional CD8 T cells are strictly dependent on CD4 T cell responses against cancer, a point that is often neglected in studies investigating cytotoxic CD8 T cell responses." (PMID 29032503, 2018). "In addition, the transcription factor has been shown to contribute greatly to the regulation of apoptosis in cancer metastasis in general and in the differentiation of T-cells to CD4+ and CD8+ T-cells in particular." (PMID 29535710, 2018). "Thus, in this manuscript we have endeavored to interrogate the phenotype and functionality of CD4+ T cell responses in cancer septic hosts." (PMID 29338031, 2018). "Low CD4 cell count and nadir, CD4 count-nadir differential, and CD4:CD8 ratio nadir were associated with increased 2-year risk of incident virus-associated cancers in models adjusted for demographics and smoking (hazard ratios 1.2–1.3 per 100 or 0.1 unit decrease, respectively; p < 0.01)." (PMID 30315476, 2018). "The high ART usage rate and the median CD4 count also support thehypothesis that referrals to cancer treatment favor patients with previouslydiagnosed HIV who are already engaged in care, or possibly those patients whocaregivers felt were more likely to benefit from cancer therapy." (PMID 30241139, 2018).